HIF1A (hypoxia inducible factor 1 subunit alpha)
Diseases named in the same sentence as HIF1A in open-access papers (continued):
Sharing a sentence is not in itself a finding about the gene and the disease.
multiple myeloma (continued). "Based on these observations, miR-210 up-regulation appears to be a prerequisite for the anti-apoptotic effect of HIF-1α in myeloma cells under hypoxic condition." (PMID 30108468, 2018). "Our date suggested that up-regulation of miR-210 is a prerequisite for the action of HIF-1α in myeloma cells." (PMID 30108468, 2018). "To investigate the effect of acute hypoxic conditions, including 5 % and 1 % O2 on HIF-1α expression, we performed real-time PCR on RNA extracted from myeloma cells." (PMID 30108468, 2018). "Although HIF-1α overexpression is seen in myeloma cells, the mechanism of HIF-1α in bone diseases still remains poorly understood." (PMID 30108468, 2018). "The current study revealed that Reelin/FAK/Syk/Akt and STAT3 pathways in myeloma cells promoted HIF1α expression and cell glycolysis." (PMID 28345605, 2017). "Reelin’s role in myeloma cell glycolysis was further supported by the clinical data from GSE24080 as high RELN-expressing patients also revealed high levels of HIF1α, PDK1, and LDHA expression." (PMID 28345605, 2017). "KD of LDHA and HIF-1α was reported to restore sensitivity to a chemodrug on multiple myeloma cell lines." (PMID 27708237, 2016). "In Multiple Myeloma (MM), HIF-1α expression has been described in several cell lines and in about 35% of CD138+ cells isolated from MM patients samples, suggesting an oxygen independent stabilization of the protein." (PMID 24732040, 2014). "The BM microenvironment is hypoxic and the hypoxia induced transcription factor HIF-1α is critically involved in the production of angiogenic factors by myeloma cells." (PMID 22245948, 2012). "Its role has been established in multiple myeloma along the HIF1α/DARS-AS1/RBM39 axis that could be a useful target in multiple myeloma." (PMID 38571491, 2024). "We thus explored whether co-immunoprecipitation of PARKIN with HIF-1α and HLA-G from myeloma cells could be expedited by IL-6." (PMID 38877399, 2024). "For example, inhibition of HIF-1α in multiple myeloma cells was shown to decrease CCL3 secretion." (PMID 38273861, 2023). "Studies have shown that HSP90 inhibitor 17-allylamino-17-demethoxygeldanamycin (17-AAG) can inhibit the production of HIF-1α protein and target genes in multiple myeloma under hypoxia, indicating that it may serve as an HIF-1α inhibitor against cancers." (PMID 36139386, 2022). "Similarly, it has been shown in patients with multiple myeloma that HIF1a and HIF2a were strongly expressed within the myeloma cells alongside an up-regulation of VEGFR." (PMID 36320041, 2022). "In addition to FOXM1, LDHA is upregulated in myeloma via HIF1A (hypoxia inducible factor 1 subunit alpha) and PPARGC1B (peroxisome proliferator-activated receptor gamma coactivator 1 beta)." (PMID 35794249, 2022). "Concurrently, we also showed downregulation of STAT5 and HIF-1α in myeloma following CLF treatment." (PMID 35646666, 2022). "They demonstrated that DARS-AS1 is regulated by HIF-1α and that DARS-AS1 regulates mTOR signaling via RBM39, thus concluding that the HIF1α/DARS-AS1/RBM39 axis could be a useful target in multiple myeloma." (PMID 36076951, 2022). "Notably, it has been shown that HIF-1α is constitutively expressed in myeloma, even under normoxic conditions." (PMID 33420361, 2021). "Interestingly, pharmacologic inhibition of HIF-1α is able to restore sensitivity to bortezomib in myeloma cell lines." (PMID 34768861, 2021). "HIF-1a is downstream of the PI3K/AKT/mammalian target of rapamycin (mTOR) pathway and is associated with the progression of myeloma cells through the transcription of several important genes concerning myeloma pathogenesis, such as VEGF and IGF-1." (PMID 33435539, 2021). "In addition, high basal MYC and HIF1α levels were observed in all multiple myeloma (MM) cell lines and primary MM cells where MYC collaborates with HIF1α to trigger VEGF production and induction of MM angiogenesis." (PMID 33572152, 2021).
multiple myeloma (continued). "Similar to miRNAs, lncRNA H19 has been confirmed to positively participate in HIF-1α nuclear translocation to drive multiple myeloma cell dissemination, although the specific molecules responsible for this procedure are unknown." (PMID 32014012, 2020). "As previously reported, MM plasma cells are protected in the vascular niche and in advanced phases of the disease, the same stromal cells acquire resistance to anti-myeloma drugs as demonstrated by the nuclear stabilization of HIF-1α in the BM endothelial cells of relapsed/refractory MM patients." (PMID 31963513, 2020). "However, the effect of anti-HIF-1α on myeloma cells was more significant under hypoxia than under normoxia culture." (PMID 30108468, 2018). "Considering that HIF-1α drastically enhances miR-210 levels in myeloma cells, we postulated that HIF-1α may affect expression of CXCR4 and VLA4 through miR-210 activation." (PMID 30108468, 2018). "The constitutive expression of HIF-1α in about 35% of Multiple Myeloma (MM) patients suggests HIF-1α suppression might be part of a therapeutic strategy." (PMID 24732040, 2014). "Consequently, a knockdown of HIF-1α and miR-210 could reduce expression of myeloma cytokines-induced bone lesion." (PMID 30108468, 2018). "In addition, we validated HIF-1α as a direct target of miR-199a-5p in myeloma cells." (PMID 24839982, 2014). "To explore it mechanistically, we established a HIF-1α-knockout (KO) cell line established by CRISPR/Cas9, and found that HLA-G expression in human myeloma cell lines under hypoxia was governed by HIF-1α." (PMID 38877399, 2024). "Consistent with the evidence above, the inhibition of HIF-1α by ING4 leads to decreased IL-8 and OPN-mediated myeloma angiogenesis." (PMID 30643005, 2019). "Fucoidan was able to reduce the expression of HIF-1a under hypoxia conditions, resulting in a reduction of VEGF expression in multiple myeloma cell lines in vitro." (PMID 30621045, 2019). "Chetomin exhibited antitumor activity in human myeloma cell lines and primary multiple myeloma cells from patients, suggestive of potential clinical value in multiple myeloma patients characterized by a high EP300 and HIF-1α expression." (PMID 31569621, 2019). "ING4 is also reportedly involved in the angiogenic switch in the progression of multiple myeloma and affects the production of the proangiogenic molecules IL-8 and osteopontin (OPN) by inhibiting hypoxia inducible factor-1 α (HIF-1α) under hypoxic conditions." (PMID 30643005, 2019). "Our findings further reveal that activated Akt and STAT3 pathways induce the upregulation of HIF1α and its downstream targets (LDHA and PDK1), leading to increased glycolysis in myeloma cells." (PMID 28345605, 2017). "In our study we also found that MMSA-1 could greatly elevated HIF-1α levels secreted by U266 cells compared with the control group cells, indicting the MMSA-1 impact on myeloma hypoxia-induced processes." (PMID 41535418, 2026). "Direct targeting of HIF-1α has also been reported to reduce disease burden in murine myeloma models, although immune cell activity was not assessed here." (PMID 40938732, 2025). "We thus developed two mouse models of myeloma xenografts in intra-bone marrow (BM) and underneath the skin, and found a strong correlation between HLA-G and HIF-1α expressions in hypoxic BM, but not in oxygenated tissues." (PMID 38877399, 2024). "Human myeloma cell lines (HMCLs) subjected to hypoxic conditions and thereafter treated with bortezomib, dexamethasone and melphalan were observed to have increased glucose metabolism, with and overexpression of LDHA and HIF-1α post-treatment." (PMID 35454812, 2022). "The direct interaction between HIF-1α and HREs in lncRNA DARS-AS1 is capable of upregulating the expression of this lncRNA, which resorts to downstream RBM39/mTOR signaling to continuously stimulate the translation of HIF-1α, hence jointly promoting myeloma malignancy." (PMID 32014012, 2020).
multiple myeloma (continued). "Notably, HIF-1α suppression in myeloma cells blocks tumoral growth in vivo and interferes negatively with angiogenesis and bone destruction." (PMID 24839982, 2014). "Interestingly, HIF1α has been regarded as the most important transcriptional factor promoting angiogenesis by upregulating pro-angiogenic genes such as VEGF, which can enhance the MVD of bone marrow and accounts for the abnormal structure of myeloma tumor vessels." (PMID 28264017, 2017). "As chaetocin demonstrated potent in vitro antineoplastic effects in solid tumour cell lines not attenuated by hypoxia-stimulated HIF-1α induction, we hypothesised that chaetocin might also have in vivo antineoplastic effects in solid tumours, akin to those observed in myeloma." (PMID 22187030, 2012). "In our HIF-1αKO myeloma cells, HIF-2α expression under hypoxia was not affected by knockout of HIF-1α." (PMID 38877399, 2024).
viral infection (62 papers, 2008 to 2026). "The study thus highlights a unique crosstalk of PHD2D4E;C127S variant with HIF1α-IFN axis under environmental pO2 in protecting or predisposing Tibetans to viral infections." (PMID 40570045, 2025). "In this study, we describe a unique crosstalk of PHD2D4E;C127S variant with environmental pO2 in protecting or predisposing to viral infections by modulating the HIF1α-interferon (IFN) axis." (PMID 40570045, 2025). "It was demonstrated that viral infections can activate hypoxia-inducible factor HIF-1α (encoded by HIF1A) by inducing local tissue hypoxia." (PMID 40634934, 2025). "Study describes a unique crosstalk of PHD2D4E;C127S variant with HIF1α under environmental pO2 in regulating the anti-viral interferon (IFN) response against the viral infections including dengue and COVID-19." (PMID 40570045, 2025). "Several viral infections cause enhanced glycolysis and metabolic reprogramming through the activation of hypoxia-inducible factor 1-alpha (HIF-1α)." (PMID 39513896, 2024). "Hypoxia-inducible factor 1 alpha (HIF-1α), the master regulator in the hypoxia response, is implicated in viral infection and innate immunity." (PMID 37210689, 2023). "HIF1α has indeed been implicated in all facets of the immune response including inflammation, responses to bacterial and viral infections, immune cell metabolism and lymphoid cell development." (PMID 32718318, 2020). "Notably, HIF-1α, IL-1β, IL-6, and IFN-β mRNAs and HIF-1α protein were induced in infected cells, suggesting that HIF-1α and immune and inflammatory cytokines are induced upon the virus infection, and HIF-1α expression is linked to immune-inflammatory cytokine expression in infected cultured cells." (PMID 34408131, 2021). "In this study, we found that SVCV-G protein interacts with hif1α-a/b and inhibits their ubiquitination, leading to the stabilization of hif1αa and hif1αb proteins, providing a direct connection between viral infection and oxygen hemostasis in fish." (PMID 39601573, 2025). "It has been found that during viral infection, HIF-1α expression is increased in infected cells, showing that its beneficial effects on the virus far outweigh those on the host." (PMID 41415822, 2025). "To investigate the mechanism of HIF1α elevation in the EGLN1c.[12C>G; 380G>C] cells upon viral infection under normoxia, we found an elevated reactive oxygen species (ROS), both total and also mitochondrial." (PMID 40570045, 2025). "Hypoxic conditions are common features of many viral infections, promoting glycolysis and further enhancing viral replication through transcription factors like HIF-1α." (PMID 40899610, 2025). "Both VSV and HSV-1 infection increased HIF1α protein levels in the lungs of WT and Irf3_P10A mice upon viral infection for 24 h." (PMID 38670937, 2024). "Taken together, we concluded that mannose elevates host tissue tolerance to damage by virus infection via antagonizing the HIF-1α-mediated proinflammatory response." (PMID 38459021, 2024). "In this line, viral infections, cancer, hypoxia, HIF-1α and cytokines (e.g., IL-12) have been found to significantly enhance furin expression." (PMID 38791489, 2024). "Previous studies indicate that Hif1α protects the host against bacterial or viral infections by promoting neutrophil survival and improving their phagocytosis." (PMID 38169405, 2024). "It was proposed that upon SARS-CoV-2 infection, SARS-CoV-2 ORF3a protein induces mitochondrial reactive oxygen species to activate HIF-1α, which in turn enhances the viral infection and aggravates inflammatory responses." (PMID 37210689, 2023). "We next investigated how HIF-1α ablation affects terminal T-cell exhaustion during chronic viral infection." (PMID 37891230, 2023).
viral infection (continued). "HIF-1α is a major angiogenesis inductor and is known to be up-regulated by distinct viral infections." (PMID 36992454, 2023). "A recent study has shown that the Wnt/β-catenin pathway promoted an inflammatory activity of macrophages following viral infection via enhanced Hif1α expression." (PMID 38162655, 2023). "Viral infections, cancer, hypoxia, HIF-1α, and cytokines (e.g., IL-12) have been found to significantly increase furin expression." (PMID 35682644, 2022). "Hypoxia inducible factor-1α (HIF-1α) is activated in host cells during viral infection and plays an important role at the site of inflammation by inducing the production of pro-inflammatory cytokines by immune cells." (PMID 35458536, 2022). "Contrary to its binding partner, HIF-1α, whose role in virus infection has been extensively investigated, the antiviral activity of ARNT has not been well studied." (PMID 35891329, 2022). "The results demonstrated that HIF-1α plays an extensive role in facilitating virus infections and inflammatory responses." (PMID 34408131, 2021). "Altogether, we presented that SARS-CoV-2 ORF3a promotes HIF-1α production to induce immune-inflammatory responses and facilitate virus infection." (PMID 34408131, 2021). "Natural killer (NK) cells require hypoxia-inducible factor-1α (HIF1α) for an optimal response to virus infection." (PMID 34396954, 2021). "Taken together, some viruses are also able to downregulate the hypoxic cellular response and modulate the effect of HIF-1α, thus overall impacting viral infections and varying their impact in the host." (PMID 34360716, 2021). "Taken together, the results suggest that ORF3a promotes HIF-1α production, inflammatory responses, and virus infection." (PMID 34408131, 2021). "Collectively, during SARS-CoV-2 infection, ORF3a induces HIF-1α, which in turn aggravates viral infection and inflammatory responses." (PMID 34408131, 2021). "siRNA silencing of HIF-1α, but not HIF-2α, in Calu-3 cells reversed the hypoxic or FG-4592-mediated suppression of viral infection, demonstrating a role for HIF-1α in repressing SARS-CoV-2 RNA replication." (PMID 33852916, 2021). "Both strains also induced hypoxia and cell stress, which appeared to be mediated in part by HIF1α, an oxygen-sensitive transcription factor that is activated in several viral infections." (PMID 33405202, 2021). "Here, we identify that SARS-CoV-2 ORF3a and host hypoxia-inducible factor-1α (HIF-1α) play key roles in the virus infection and pro-inflammatory responses." (PMID 34408131, 2021). "Altogether, our results suggest that ORF3a promotes HIF-1α production, immune-inflammatory responses and virus infection through inducing the Mito-ROS signaling." (PMID 34408131, 2021). "So, due to viral effect on the innate immunity reaction and because of HIF-1α effect on the promotion of viral infection, understanding the role of HIF-1α on innate immunity response can be effective for introducing new strategies against viral infection." (PMID 33139969, 2020). "The identification of the role of HIF1α in viral infection suggests a unique opportunity for HIF1α inhibitors to be used as anti-viral drugs." (PMID 32718318, 2020). "So, because of autophagy recruitment of SARS-CoV-2 in host cells to increase its proliferation and progression, HIF-1α inhibition activity is the other way to suppress viral infection." (PMID 33139969, 2020). "In fact, adenoviral infection led to the transcriptional down-regulation of HIF-1α and the reduction of hypoxia-specific gene expression during the late phase of viral of infection." (PMID 32244697, 2020). "Viral infection can induce HIF-1α activation which the net consequence of its activation can give favors the pathogen rather than the host." (PMID 33139969, 2020). "Many studies have demonstrated that HIF-1α participates in the cellular response to viral infections." (PMID 32208814, 2020).